NID1 (nidogen 1)
Diseases named in the same sentence as NID1 in open-access papers (continued):
Sharing a sentence is not in itself a finding about the gene and the disease.
glioma (5 papers, 2020 to 2025). A benign or malignant brain and spinal cord tumor that arises from glial cells (astrocytes, oligodendrocytes, ependymal cells). "TIMER database analysis showed that NID1 expression in low-grade gliomas was associated with tumor infiltration of B cells, CD4+ and CD8+ T cells, macrophages, neutrophils, and dendritic cells." (PMID 33735110, 2021). "Kaplan-Meier survival curve analysis showed that low-grade gliomas patients with high NID1 expression were associated with shorter overall survival." (PMID 33735110, 2021). "It has been recently reported that the tumor suppressor miR-1298-3p reduces the proliferative and invasive abilities of glioma cells by downregulating the BM-related gene NID1." (PMID 36292695, 2022). "NID1 silencing enhanced in vitro apoptosis and the temozolomide sensitivity of U251 and U87-MG glioma cells." (PMID 33735110, 2021). "Oncomine, GEPIA, UALCAN, CCGA database analyses showed that NID1 transcript levels were significantly upregulated in multiple cancer types, including gliomas." (PMID 33735110, 2021). "Quantitative RT-PCR analyses confirmed that NID1 expression was significantly upregulated in glioma tissues compared to paired adjacent normal brain tissue samples (n=9)." (PMID 33735110, 2021). "MiR-1298-3p agonist downregulated the NID1 and vimentin levels, but upregulated the level of E-cadherin in glioma cells." (PMID 32355035, 2020). "We have found that overexpression of miR-1298-3p downregulates the levels of NID1 and vimentin, and upregulates the level of E-cadherin in glioma cells, indicating that overexpression of miR-1298-3p inhibits glioma cell invasion." (PMID 32355035, 2020). "The basement membrane protein Nidogen-1 (NID1) was identified as a direct binding target of miR-1298-3p in glioma cells." (PMID 32355035, 2020). "Finally, miR-1298-3p exerts an inhibitory effect in glioma cells by downregulating nidogen-1, and has a similar negative regulatory role in cervical cancer cells." (PMID 38827810, 2024). "We investigated the prognostic significance of nidogen-1 (NID1) in glioma." (PMID 33735110, 2021). "NID1 is thus a potential prognostic biomarker and therapeutic target in low-grade glioma patients." (PMID 33735110, 2021). "Specifically, NID1 was related to open chromatin regions in both the LGG and GBM samples, demonstrating the different functions of genes between the two glioma subtypes and further confirming the diversity of gene transcription regulation between them." (PMID 41473442, 2025). "In addition, our results indicate that miR-1298-3p functions as a tumor suppressor that inhibits proliferation and invasion of glioma cells by suppressing the NID1 expression, and suggest that miR-1298-3p might serve as a potential biomarker for the glioma treatment." (PMID 32355035, 2020).
hepatocellular carcinoma (5 papers, 2021 to 2025). A malignant tumor that arises from hepatocytes. "NID1 is a glycoprotein present in the basement membrane, reported to promote cell migration by being present on EVs derived from hepatocellular carcinoma cells." (PMID 37528162, 2023). "In hepatocellular carcinoma, nidogen 1 (NID1) in EVs promote tumor cell colonization and extrahepatic metastasis by enhancing angiogenesis and lung endothelial permeability and promoting the formation of pre‐metastasis niches in the lung." (PMID 34977870, 2021). "Co-treatment with KPA also decreased the expression of genes, regulating the progression of fibrosis (e.g., COL6A3, AEBP1, SPARC, TNC, LAMB1, BGN) and hepatocellular carcinoma (e.g., COL4A1, COL4A2, TUFT1, VCAN, NID1)." (PMID 39404414, 2024). "Importantly, the perturbation of the lung endothelial wall by tumor-EVs was also demonstrated in a model of hepatocellular carcinoma (HCC), where tumor-EVs carrying Nidogen 1 (NID1) enhanced angiogenesis and pulmonary endothelial permeability." (PMID 37207158, 2023).
lung carcinoma (4 papers, 2014 to 2020). "Upregulation of NID1 promotes proliferation and metastasis in endometrial and lung cancer." (PMID 32355035, 2020). "Thus, further studies are needed to investigate whether B-Myb activates ERK and Akt signaling pathways at least partially though up-regulation of FLT4, COL11A1, and NID1 in lung cancer cells." (PMID 28555007, 2017).
colorectal cancer (3 papers, 2023 to 2025). A primary or metastatic malignant neoplasm that affects the colon or rectum. "Taken together, those data determined that NID1 indeed plays a role in promoting colorectal cancer cells growth and invasion." (PMID 41281746, 2025). "Taken together, NID1 is a pivotal downstream gene of ETV4/LOXL2 promoting aggressive phenotype in colorectal cancer." (PMID 41281746, 2025). "Secreted NID1 was shown to act as a paracrine to induce EMT and promote colorectal cancer progression." (PMID 40332526, 2025). "We next to verify whether ETV4/LOXL2/NID1 induce EMT transformation and metastasis in colorectal cancer cells by activating ERK signaling pathway." (PMID 41281746, 2025).
endometrial cancer (3 papers, 2017 to 2021). Primary or metastatic malignant neoplasm involving the endometrium (mucous membrane that lines the endometrial cavity). "In agreement with our observation, inhibition of NID1 reduced the migration and invasion of ETV5-overexpressed endometrial cancer cells." (PMID 28416770, 2017). "Similarly, ETV5 induces the epithelial–mesenchymal transformation of endometrial cancer through transcriptional activation of the nidogen-1 (NID1) and nuclear protein 1 (NUPR1) genes, participating in the process of endometrial cancer invasion." (PMID 34736492, 2021). "In addition, inhibition of NID1 reduced the migration and invasion of ETV5 overexpressing endometrial cancer cells." (PMID 28416770, 2017). "Its role in cancer metastasis has been described in ovarian and endometrial cancer; however, its role in HCC remains uncertain, and the significance and existence of NID1 in EVs of HCC have never been reported." (PMID 33173740, 2020).
prostate carcinoma (3 papers, 2019 to 2023). A carcinoma that arises from epithelial cells of the prostate gland. "Noteworthy is the identification, by us and other researchers, of tumor-suppressing proteins like serine protease 8 (PRSS8) and nidogen 1 (NID1) within the urine of prostate cancer patients." (PMID 38250812, 2023). "The protein NID1 in urine and its recombinant protein reduced the EdU-based proliferation and scratch-based motility of TRAMP prostate cancer cells." (PMID 38250812, 2023).
systemic lupus erythematosus (3 papers, 2019 to 2025). An autoimmune multi-organ disease typically associated with vasculopathy and autoantibody production. "While our data found a classical engagement of C3 with C3 and C4, nidogen-1 (NID1), and plasminogen (PLG), C3-LHF1 also engaged with other lupus- and autoimmune-related proteins, such as WDR1, RPL22, and PXDN, supporting its mechanism of interacting with surface binders." (PMID 41145914, 2025).
breast tumors (2 papers, 2021 to 2025). "Taken together, these findings suggest that nidogen-1 expression is reduced in CAFs in breast tumors compared with healthy tissue." (PMID 41181108, 2025). "We previously identified nidogen-1 as being downregulated in 4T1 breast tumors compared with healthy mammary fat pad." (PMID 41181108, 2025). "We found that in both the Curtis Breast dataset and the Karnoub Breast dataset, nidogen-1 is downregulated in breast tumors compared to healthy breast tissues." (PMID 41181108, 2025). "We found that nidogen-1 is expressed by fibroblasts but not cancer cells, and nidogen-1 is downregulated in breast tumors compared to healthy mammary gland." (PMID 41181108, 2025).
cataract (2 papers, 2019 to 2022). Partial or complete opacity of the crystalline lens of one or both eyes that decreases visual acuity and eventually results in blindness. "Particularly, mutations in three of them, AGBL4, DYNC2H1, and KIZ, cause retinal pathologies in humans, while a NID1 mutation was found to be the cause of the development of recessive cataracts in Romagnola cattle." (PMID 36669004, 2022). "It is very likely that congenital bilateral cataracts may be genetically heterogeneous and not yet known variants in genes other than CPAMD8 and NID1 are involved." (PMID 31877171, 2019).
coloboma (2 papers, 2023 to 2024). An abnormality in which a part of a structure in one or both eyes is missing. "Our cross-species meta-analysis also provided evidence that genes previously associated with coloboma causation in model organisms, such as VAX1, NTN1, and NID1, should be more widely recognised as possible human MAC candidates." (PMID 36830662, 2023). "Among these were the known human MAC genes TENM3, SMOC1, PAX2, ALDH1A3, and BMPR1B, in addition to NID1, VAX1, and NTN1, which have been previously identified as MAC or coloboma candidates based on animal studies." (PMID 36830662, 2023). "The conserved expression in the OFM across species and the coloboma phenotype observed in nid1 morphant zebrafish suggest an essential role for nidogen in optic fissure closure and further investigation of human orthologs NID1 and NID2 as novel candidate coloboma genes." (PMID 38821055, 2024).
colon cancer (2 papers, 2007 to 2013). "Examples include α-4-integrin, which is silenced in colon cancer, and basement proteins Nidogen 1 and 2 (NID 1 and 2), which regulate integrin function and are silenced in some cancer cells." (PMID 24152442, 2013).
cytomegalovirus infection (2 papers, 2021 to 2022). A herpesvirus infection caused by Cytomegalovirus. "Next, cytomegalovirus infection in humans has been shown to cause downregulation of nidogen 1 (Nid1) and to degrade the protein it encodes, thus impacting vascular wall integrity and allowing further viral spread." (PMID 36142395, 2022). "Nid1, on the other hand, is known to be adversely affected by cytomegalovirus infection in humans in such a way as to obliterate the normal functions of the nidogen 1 protein." (PMID 34415947, 2021).
diabetic kidney disease (2 papers, 2022 to 2024). Progressive kidney disorder caused by vascular damage to the glomerular capillaries, in patients with diabetes mellitus. "Nidogens have been shown to be upregulated in the mesangial matrix and the GBM in glomerular disorders, such as lupus nephritis, IgA nephropathy, and diabetic nephropathy, but it is a novelty for NID1 to be increased in MCD, presumably as adaptation during FPE." (PMID 38891801, 2024).
liver fibrosis (2 papers, 2012 to 2022). "VEGF-R1, ANGPTL-4, Nidogen-1 have not been reported to be associated with the occurrence of liver fibrosis." (PMID 35659360, 2022).
Obesity (2 papers, 2024 to 2025). Accumulation of substantial excess body fat. "The endothelial-specific obesity-induced DEGs downregulated by obesity included Nid1, Sparc, and Ogn, which play a role in angiogenesis." (PMID 41310161, 2025). "Obesity mostly downregulated endothelial-specific DEGs, including Nid1, Sparc, and Ogn, while Ripor2 was the only upregulated endothelial-specific DEG." (PMID 41310161, 2025).
Stroke (2 papers, 2021 to 2023). Sudden impairment of blood flow to a part of the brain due to occlusion or rupture of an artery to the brain. "Expression of basement membrane components was also increased in astrocytes after stroke, including isoforms of proteins that compose the majority of brain vascular basement membrane (collagen IV α1 and α2; laminin α4, α5, β1, and γ1; and nidogen-1 and −2; Kang and Yao, 2020)." (PMID 33910014, 2021). "To date, there is no phenotypic OMIM listing for NID1-related phenotype although we have previously published congenital stroke in two siblings who shared a novel homozygous splicing variant confirmed by RT-PCR." (PMID 38098057, 2023).
type 2 diabetes (2 papers, 2022). "Key mediators of the injury responses in islets transgenic for human IAPP or those from individuals with type 2 diabetes include STAT3, NF-κB, ESR1 and CTNNB1 by transcription factor analysis and COL3A1, NID1 and ZNF800 by gene regulatory network analysis." (PMID 34554282, 2022).
viral infection (2 papers, 2018 to 2021). "The viral infection caused down-regulation of the nidogen 1 gene and degradation of the protein it encodes: a basement membrane protein crucial for the integrity of vascular walls." (PMID 34415947, 2021). "Nid-1 was shown to be required for a virus infection step that occurs after NSD-1 functions." (PMID 29743532, 2018).
arterial disease (1 paper, 2021). "It would be interesting to examine whether those secreted proteins (Bgn,Cpe,Emillin1,Fstl1,Nid1,Mgp,Sparc, and Spp1) validated by our ISH are the result of the arterial disease or play a direct causative role." (PMID 34762601, 2021).
B-cell neoplasm (1 paper, 2025). A group of heterogeneous lymphoid tumors generally expressing one or more B-cell antigens or representing malignant transformations of B-lymphocytes. "Consulting the DEPMAP database, consisting of the gene expression data of human cancer cell lines, we observed a specific expression of NID1 in AML, myeloproliferative and few mature B-cell neoplasm cell lines compared to other hematological malignancies." (PMID 40243655, 2025).
congenital cataracts (1 paper, 2019). "In order to screen for further not yet known variants within candidate genes CPAMD8 and NID1 involved in bovine congenital cataracts, we analyzed whole genome sequencing (WGS) in three affected Holstein calves, two unaffected dams of affected calves and one unaffected herd mate." (PMID 31877171, 2019). "The candidate gene NID1 did not segregate in Holsteins nor in any other cattle breeds genotyped here and thus, can be excluded for congenital cataracts in Holsteins which is in agreement with a previous study." (PMID 31877171, 2019).
diabetes (1 paper, 2023). "Similarly, Wnt-5a treatment of wounded diabetic organ-cultured corneas reduced healing time by 37% (p<0.05) vs BSA treatment (control), with acquisition of normal-like patterns of LESC markers K15 and K17, and diabetes-suppressed integrin α3β1 and nidogen-1." (PMID 37460827, 2023).
diabetic retinopathy (1 paper, 2021). "We observed the species R. intestinalis associated with rs79499638 (P = 3.81 × 10−8) and rs760646544 (a insertion of CTGTT, P = 1.75 × 10−8) near PLXDC2 (related to nidogen-1 measurement and diabetic retinopathy in GWAS catalog)." (PMID 33563976, 2021).
Fever (1 paper, 2025). Body temperature elevated above the normal range. "Results showed that the levels of candidate proteins including HSP90α, VCAM1, PSMA1, and NID1 were higher in the fever stage of SFTS patients compared with healthy controls, almost reaching plateaus in the MOD stage, and the concentrations were decreased in the convalescent stage." (PMID 39973934, 2025).
glaucoma (1 paper, 2024). Increased pressure in the eyeball due to obstruction of the outflow of aqueous humor. "Similarly to our findings, the upregulation of CRI (complement component 1R) and NID1 (nidogen 1) was detected in aqueous humor from several glaucoma types as compared to cataract samples." (PMID 39000104, 2024).
Hirschsprung disease (1 paper, 2020). Hirschsprung disease (HSCR) is a congenital intestinal motility disorder that is characterized by signs of intestinal obstruction due to the presence of an aganglionic segment of variable extent in the terminal part of the colon. "It was previously reported that miR-192 suppresses the progression of Hirschsprung's disease by directly targeting NID1, and that NID1 acts as a tumor promoter in NSCLC." (PMID 32357143, 2020).
Infertility (1 paper, 2025). "Also, menstrual blood serum was characterized as a less invasive source of infertility biomarkers, where EMILIN1, TRIP6, LAMB1, LAMC1, NID1, APOB, APOA4 were detected as the main differences in uIF patients as compared to healthy controls." (PMID 40861859, 2025).
ischemia (1 paper, 2021). A hypoperfusion of the BLOOD through an organ or tissue caused by a PATHOLOGIC CONSTRICTION or obstruction of its BLOOD VESSELS, or an absence of BLOOD CIRCULATION. "We next asked if the protective and antifibrotic effect of NID1 during ischemia is organ‐specific or would be of benefit in other noncardiac therapeutic areas, such as islet transplantation, where ischemia and the survival of transplanted islets are a major therapeutic roadblock." (PMID 33643791, 2021).
kidney injury (1 paper, 2018). Trauma to the kidney. "Interestingly, a fragment of nidogen-1 migrating at ~50 kDa was also detectable in urine from diabetic patients with kidney injury as determined by UACR, perhaps corresponding to a cleavage product." (PMID 29854459, 2018).
Lassa fever (1 paper, 2021). A viral hemorrhagic fever that is caused by the Lassa virus, which is transmitted by contact with infected rodents; it is characterized by fever, headache, malaise, myalgia, and hearing loss. "Genes involved in extracellular matrix and cell-adhesion were also modulated, particularly during fatal Lassa fever (NID1, TIMP3, ITGA11, TGM2, MMP8/9, OLFM4, PCDH20, and CADM3), as well as some others involved in coagulation (SERPIN, TFPI2) and apoptosis (CLU, BCL2L14)." (PMID 33398113, 2021).
liver cancer (1 paper, 2020). An epithelial or non-epithelial malignant neoplasm that arises from the liver. "Nidogen 1‐enriched extracellular vesicle (EV‐NID1) activates pulmonary fibroblasts to secrete tumor necrosis factor receptor 1 (TNFR1) which favors lung metastasis of liver cancer." (PMID 33173740, 2020).
Neonatal sepsis (1 paper, 2025). Systemic inflammatory response to infection in newborn babies. "The additional decreases in structural ECM proteins such as brevican, nidogen-1 and −2, and fibronectin suggest that neuroinflammatory damage in neonatal sepsis may involve degradation of the ECM, potentially contributing to long-term neurological complications." (PMID 40927580, 2025).
neuroblastoma (1 paper, 2024). Neuroblastoma (NB) is the most common solid, extracranial childhood tumor. "When nidogen-1 was transiently expressed with this fusion protein (HA-eLAR-Myc) in mouse neuroblastoma-2a (N2a) cells and immunoprecipitated in the presence of HCT, we found that eLAR was specifically associated with nidogen-1." (PMID 38977849, 2024).
osteoporosis (1 paper, 2022). A condition of reduced bone mass, with decreased cortical thickness and a decrease in the number and size of the trabeculae of cancellous bone (but normal chemical composition), resulting in increased fracture incidence. "Furthermore, the generally acidic osteoporotic bone in untreated osteoporosis could support bone metastasis with the secretion of proteins such as COL1A1, COL4A2, NID1, FBLN1, and NRP2." (PMID 35159353, 2022).
periodontitis (1 paper, 2025). An acute or chronic inflammatory process that affects the tissues that surround and support the teeth. "The upregulation of genes encoding components of the extracellular matrix (ECM) and basement membrane, such as versican (Vcan) and nidogen-1 (Nid1), was also found in gingival tissue with periodontitis." (PMID 40076622, 2025).
salivary gland adenoid cystic carcinoma (1 paper, 2025). An adenoid cystic carcinoma arising from the salivary gland. "Interestingly, in salivary gland adenoid cystic carcinoma, under hypoxic conditions, HIF-1α binds to the promotor of NID1 to upregulate NID1 expression and increases cancer cell invasion and migration via the PI3K/AKT-EMT pathway." (PMID 40243655, 2025).
schizophrenia (1 paper, 2024). A major psychotic disorder characterized by abnormalities in the perception or expression of reality. "A recent study found that Nidogen-1 was one of four proteins significantly reduced in patients with schizophrenia." (PMID 38550383, 2024). "The progressive neurodegeneration in schizophrenia is consistent with the previously discussed role of Nidogen-1 in maintaining BM structure and may indicate a prosurvival role of Nidogen-1 in Schwann cell development." (PMID 38550383, 2024).